LEP (leptin)
Diseases named in the same sentence as LEP in open-access papers (continued):
Sharing a sentence is not in itself a finding about the gene and the disease.
Obesity (continued). "As a strong risk factor for many diseases, obesity predisposes the body to a pro-inflammatory state via increased levels of inflammatory mediators such as tumor necrosis factor (TNF)-α, interleukin (IL)-6, leptin, and reduced levels of adiponectin secreted by adipose tissue." (PMID 34576066, 2021). "In addition, since obesity seems to have a promising role in AD microbiota, a new research avenue on the role of leptin in the microbiota of AD patients may be considered in future studies." (PMID 34827640, 2021). "Increased leptin positively correlated with systolic blood pressure and pulse pressure and negatively with arterial compliance in obese/overweight hypertensive, compared to obese/overweight normotensive African women independently of obesity, insulin resistance, and age." (PMID 34202323, 2021). "Thus, db/db mice develop obesity because of leptin resistance." (PMID 34356303, 2021). "Similarly, metabolic failures and obesity features have also been observed when leptin deficiency develops in adulthood, highlighting that the lack of leptin can promote obesity even though its deficiency is not congenital." (PMID 34208585, 2021). "Moreover, leptin can lead to lipid accumulation and further aggravate obesity." (PMID 34485124, 2021). "However, the presence of obesity may represent a confounding factor in defining the leptin as an early marker of GDM." (PMID 34652617, 2021). "Although there is evidence concerning the role of both obesity and leptin in many diseases and in the immune system (e.g., leptin promotes other skin and allergic diseases), we should take into account the high degree of heterogeneity of AD, which could affect leptin analyses." (PMID 34827640, 2021). "However, consistently high levels of circulating leptin may contribute to ‘hyperleptinemia’ or leptin resistance in individuals with obesity, thus reducing the hypothalamus' response to leptin and current energy stores." (PMID 32741068, 2021). "Moreover, the E2-dependent downregulation of leptin and its interaction with gut microbiota may provide an essential braking mechanism against the development of diet-induced obesity." (PMID 34436440, 2021). "Therefore, leptin could play a significant role in developing severe COVID-19 infection in patients with obesity." (PMID 34220807, 2021). "The genetically induced hyperphagia and obesity in db/db mice, ob/ob mice, BTBR.Cg-Lepob/WiscJ ob/ob (BTBR ob/ob) mice and Zucker obese fa/fa rats are associated with the development of insulin resistance, Type 2 diabetes mellitus (T2DM), and altered leptin signaling." (PMID 34063911, 2021). "Moreover, having identified that obesity-related inflammation may have a fundamental role, EIB in infants with asthma and obesity measured by CPET seems to linearly correlate with leptin and inversely correlate with adiponectin concentration." (PMID 34835964, 2021). "Obesity is a very complex abnormal state, accompanied by various physiological and molecular alterations, which involves the complicated roles of adipokines (leptin, adiponectin, resistin, visfatin, and SFRP5), insulin, IGF, sex hormone, and chronic inflammation." (PMID 34350120, 2021). "Therefore, understanding endospanin’s role in bone dynamics, especially given the uniqueness of gene loci for these genes in Teleost fish, will likely pay dividends toward understanding the role of leptin resistance in obesity in addition to its role in bone dynamics." (PMID 35069248, 2021). "However, it is still unknown whether leptin plays a role in the pathogenesis of obesity-induced hypertension and SDB in NZO mice." (PMID 34276408, 2021). "Increased circulating leptin levels may also contribute to enhancing basal lipolysis in obesity." (PMID 34575649, 2021).
Obesity (continued). "In addition to NKG2D, we focused on its ligand, the MHC class I poly-peptide-related sequence A (MICA), as well as markers indicating increased donor graft immunogenicity (HLA-DRB), immune activation (CCL19), obesity (Leptin) and alternative Natural Killer (NK) cell receptors (DNAM-1)." (PMID 34354697, 2021). "Together, correction of plasma leptin and adiponectin levels and improvement in markers of central leptin resistance suggest that SH‐BC‐893 could be effective as an interventional agent for diet‐induced obesity." (PMID 34231322, 2021). "For example, leptin-deficient mice become obese yet they do not develop knee OA, suggesting leptin may play a key role in obesity-induced OA." (PMID 33752736, 2021). "Finally, we understand that leptin sensitivity is best known for its role in obesity, and indeed, mice made extremely leptin sensitive via endospanin knockdown are resistant to obesity." (PMID 35069248, 2021). "For these reasons, leptin supplementation to ob/ob mice normalizes their metabolic status, whereas leptin sensitizers such as neutralizing leptin antibodies, hypothalamic ER stress relievers, and other molecules have taken center stage in obesity drug development." (PMID 34064308, 2021). "However, most persons with diet-induced obesity develop leptin resistance." (PMID 33920379, 2021). "Obesity caused leptin to be higher when compared to non-obese individuals (p < 0.001)." (PMID 34957187, 2021). "Therefore, lifestyle and dietary modifications could be a promising anti-obesity therapeutic to restore leptin signalling, similarly to what has been observed after PNS treatment." (PMID 34208585, 2021). "Therefore, the potential therapeutic strategy for obesity-related OA could be by inhibiting the leptin signal via the reduction of leptin levels and enhancement of SOCS3 expression, or by directly suppressing TLR4 expression." (PMID 34457118, 2021). "In our study, the finding of a direct correlation between changes in leptin levels and impulsivity is in line with a previous study highlighting in 5214 participants that some personality traits, such as impulsivity, are most consistently related to obesity and higher levels of leptin." (PMID 34173157, 2021). "This suggests that butyrate-producing L. salivarius may be considered as a potential treatment for obesity in infants by reducing inflammatory cytokines and regulating leptin/insulin levels, but this requires further investigations and elucidation through future RCTs." (PMID 34835958, 2021). "Indeed, circulating levels of leptin are proportional to the adipose tissue mass and, thus, the enhanced secretion of leptin might be a consequence of obesity." (PMID 34208585, 2021). "DIO rodent models developed severe obesity, prediabetes or diabetes, resulting in BW gain that was mediated by an increase in body fat and liver weight; in addition, these models showed an increased level of leptin, with disturbed metabolic parameters and increased lipogenesis in adipose tissue." (PMID 34867411, 2021). "However, human obesity shows increased leptin levels, which differ from those in ob/ob mice." (PMID 34074279, 2021). "Indeed, recent studies showed that re-sensitisation of leptin signalling mediated by neutralising antibodies restores both leptin and insulin sensitivity, promoting weight lowering and thermogenic activation and thus constituting a promising therapy against leptin resistance in obesity." (PMID 34208585, 2021). "Interestingly, specific deletion of Kif3a or Tg737 using synapsin 1-cre (Syn1-cre) led to similar results of obesity and leptin resistance, indicating that neuronal primary cilia may play important roles in the regulation of body weight homeostasis." (PMID 34211092, 2021). "Therefore, we can suspect that a higher intake of total fat, SFA, MUFA, and PUFA in PCOS individuals may increase the leptin/ghrelin ratio and contribute to the development of obesity." (PMID 32927680, 2020).
Obesity (continued). "The excess fat mass that characterizes obesity is produced by an expansion of adipose tissue not only as an inert energy reservoir, but also as an endocrine organ producing various adipokines such as leptin, adiponectin, adipsin, resistin, and approximately 50 biologically active proteins." (PMID 32947606, 2020). "In addition to leptin, circulating levels of free fatty acids and cholesterol are increased with obesity, and these too may impact CD8+ T cell function, although there is currently only circumstantial evidence to support this." (PMID 33170123, 2020). "Therefore, the activation of inflammatory pathways other than the vagus nerve interferes with insulin and leptin signaling in the brain and also in peripheral tissues, contributing to insulin resistance in obesity and metabolic disorders, such as type 2 diabetes." (PMID 33353562, 2020). "Fructose affects the sensation and response of the central nervous system via elevation in cannabinoid 1 (CB1) receptor messenger RNA (mRNA) and leptin, hence, it might disturb hunger and satiety control, as well as contribute to the development of obesity and metabolic complications." (PMID 31935815, 2020). "Additionally, a bidirectional influence between leptin and insulin exists, with hyperinsulinemia enhancing leptin production and increased free leptin levels increasing insulin resistance, with “leptin resistance” and IR usually coexisting in obesity, even at young ages." (PMID 33137934, 2020). "In the present review, we discuss the data emerged from research of leptin in obesity as an inflammatory mediator sustaining multifactorial diseases and how this knowledge could be instrumental in the design of leptin-based manipulation strategies to help restoration of abnormal immune responses." (PMID 32824322, 2020). "Moreover, leptin and microglia were recently identified as key players in hypertension-provoking influences of obesity, although the specific brain sites and cell types involved in this interaction are unknown." (PMID 32538782, 2020). "Thus, we can speculate that leptin might play a crucial role in the link between obesity and drug-resistant phenotypes in breast cancer." (PMID 32260113, 2020). "However, we recognize that GIO models are not the best tools, being leptin deficient and showing an obesity that does not reflect the characteristics of pancreatic cancer patients." (PMID 32411709, 2020). "However, paradoxically, elevated levels of leptin in obese hosts, especially diet-induced obesity, may indicate the development of leptin resistance, which may play a role in the development of obesity." (PMID 32244807, 2020). "Hence, it is possible that, rather than lacking leptin per se, other metabolic abnormalities in these obese mice are mediating the hepatocyte hyperplasia, probably related to the role of obesity as a major risk factor for liver carcinogenesis." (PMID 33316927, 2020). "In a dose‐dependent manner, leptin induces proliferation, mitogenic, and antiapoptotic effects when it is cultured with human PCa cell lines, revealing that chronic exposure to high‐leptin levels as in obesity could promote the progression of PCa via the MAPK and PI3K signaling cascade." (PMID 32573960, 2020). "Therefore, in obesity-related high plasma leptin conditions, inflammation would occur when signal transduction pathways was activated, such as the activation of NFκβ, by the binding of leptin to its receptor and subsequent release of the inflammation factors, for instance TNFα." (PMID 32824322, 2020). "In addition, the role of chronic inflammation in the development of leptin resistance, which may lead to obesity is also reviewed in the present work." (PMID 32824322, 2020). "Therefore, teasaponin has important effects in improving glucose tolerance, central leptin sensitivity, and hypothalamic leptin signaling, and it might be a potential candidate as therapeutic intervention for obesity and GDM." (PMID 32630697, 2020).
Obesity (continued). "The leptin resistance in the hypothalamus impairs the weight control that may lead to obesity." (PMID 32824322, 2020). "More precisely, the altered gut microbiota composition by prebiotics improves leptin sensitivity in diet-induced obese and type 2 diabetic mice, suggesting the gut microbiota modulations could be a novel therapeutic target to reset leptin sensitivity during obesity." (PMID 32824322, 2020). "Specific adipokines, such as leptin and adiponectin, are reported to be involved in the etiology of metabolic diseases, and obesity leads to the dysregulation of adipokine secretion; therefore, adipokines may represent the link between obesity and energy homeostasis." (PMID 32561824, 2020). "Thus, leptin may play an important role in the induction of psoriasis, especially in patients with obesity." (PMID 32823524, 2020). "Obesity can lead to metabolic disturbances, such as higher levels of pro inflammatory cytokines (e.g. tumour necrosis factor-α and interleukin-6), adipokines (e.g. glucose, insulin, and leptin), and endogenous sex steroids, which may increase cancer risk." (PMID 33079929, 2020). "Therefore, it seems to be important to assess whether the non-obese PCOS group has any metabolic abnormalities and what kind of abnormalities they present before the onset of obesity, which could be accompanied by leptin resistance." (PMID 32927680, 2020). "Much less is known about whether or how obesity impacts the relationship between leptin and (L)SNA." (PMID 32160920, 2020). "Moreover, it has been shown that in metabolic diseases, such as obesity and diabetes, leptin signaling may be impaired, indicating its important role in the etiology and pathophysiological manifestations of these conditions." (PMID 33322719, 2020). "However, intermittent hypoxemia and sleep fragmentation may stimulate leptin secretion, and therefore, leptin might prevent respiratory depression in obesity, which could in turn explain increased leptin concentrations among patients with OSAS." (PMID 31055727, 2020). "The concept of leptin resistance during obesity could be due to several molecular mechanisms." (PMID 32069871, 2020). "Finally, higher levels of insulin (p = 0.039) and leptin (p = 0.082) were detected in the blood of GF mice receiving feces from aged versus adult mice, which is consistent with the changes seen in obesity." (PMID 33046129, 2020). "Therefore, leptin and adiponectin, as the most plenteous and the best-studied obesity-related adipokines, may play an important role in the development of HCC." (PMID 33256658, 2020). "Therefore, hyperleptinemia and hypothalamic inflammation in diet-induced obesity may activate a common negative regulator of leptin signaling, SOCS3 or PTP1B, and contribute to central leptin resistance." (PMID 32630697, 2020). "Although leptin may have a role as a nutritional regulator of immunity in the setting of both under- and overnutrition, we will focus here on the effects of leptin on the immune system in the context of obesity." (PMID 33584724, 2020). "This suggest that resveratrol might improve the leptin sensitivity in obesity." (PMID 32630697, 2020). "However, in pathological conditions such as obesity, dysfunctional adipocytes mostly produce and release pro-inflammatory adipokines such as leptin, tumour necrosis factor-α (TNFα), interleukin 6 (IL-6), interleukin 18 (IL-18), or resistin, which have atherogenic effects." (PMID 33081064, 2020). "Some studies found that the leptin/adiponectin ratio could be an important parameter in obesity." (PMID 32085704, 2020). "Thus, obesity may have affected univariate analyses of leptin and the MBDA score, although it seems unlikely that obesity alone could explain the large differences observed between patients who were in remission vs. those who were not." (PMID 32580789, 2020).
Obesity (continued). "The aim of this study was to evaluate the relationship between adipocytokines (leptin, ghrelin, and chemerin), inflammation (sVCAM1—soluble vascular adhesion molecule 1, sICAM1—soluble intercellular adhesion molecule 1), and insulin resistance in the presence of obesity and diabetes mellitus." (PMID 32858998, 2020). "However, in obesity status, the dysfunctional adipocyte may lead to an irrepressible increase in circulating leptin." (PMID 33597945, 2020). "Potential cell-extrinsic host milieu may include several obesity-related factors that include components of the adipocyte secretome, such as hormones (e.g., estrogens), growth factors (e.g., insulin-like growth factor I), and adipokines (e.g., leptin)." (PMID 32260113, 2020). "Therefore, this study was performed to evaluate the preventive and curative effects of CM resin alcoholic extract against HFD induced obesity and dyslipidemia with the respect to its impact on the expression of obesity development related cytokines, leptin, adiponectin and UCP1 in rats." (PMID 32197395, 2020). "Several lines of evidence have suggested that periconceptional alcohol use may have a negative impact on adult offspring, including increased obesity risk, altered plasma lipids, leptin profiles, and liver steatosis." (PMID 32974100, 2020). "Therefore, new research into nutritional mechanisms that restore leptin metabolism and signals of energy homeostasis may inspire new treatment options for obesity-related disorders such as GDM." (PMID 32630697, 2020). "However, in obesity these neurons become resistant to the actions of Leptin." (PMID 32636807, 2020). "Moreover, leptin resistance affects the regulation of ROS in obesity which leptin increases may also regulate the accumulation of ROS in the immune response." (PMID 32625169, 2020). "Many human and animal studies have demonstrated that sOb-R levels are inversely correlated with plasma levels of leptin, BMI, and adiposity, suggesting that low levels of the soluble isoform contribute to obesity-related hyperleptinemia and subsequently, leptin resistance." (PMID 33210603, 2020). "Particularly, the concept has been expanded to encompass the idea that this low level of thermogenesis (and perhaps a low metabolic rate in general) could promote the development of obesity (and consequently that leptin should in itself promote thermogenesis and thus promote weight loss)." (PMID 31774114, 2020). "Additionally, obesity might result in leptin resistance, with consequent excessive leptin levels and disproportionate release of cortisol." (PMID 32557131, 2020). "In contrast, PD-1 expression was not increased in T-cells from leptin-deficient or ObR-deficient mice, providing a mechanistic explanation for how response to this form of immunotherapy is potentially enhanced in the setting of obesity." (PMID 33604295, 2020). "The adiponectin/leptin ratio is a functional biomarker of adipose tissue inflammation and a good indicator of a dysfunctional adipose tissue, which may be a useful estimator of obesity and metabolic syndrome." (PMID 32326613, 2020). "It is thought that leptin may be an important mediator between obesity and the development of CVDs." (PMID 32121175, 2020). "Furthermore, obesity and total fat mass should also be taken into consideration when measuring BAT activity in response to food, due to the positive association between leptin and body fat stores and the negative association between obesity and BAT activity." (PMID 32927664, 2020). "All these results indicated that fat factor, specifically leptin, might be the mechanism of obesity related TMJOA and excessive mechanical force related TMJOA, and the protective effect on the TMJOA-like changes of simvastatin was exerted by inhibiting leptin expression." (PMID 33060739, 2020).